TLR2 (toll like receptor 2)
Diseases named in the same sentence as TLR2 in open-access papers (continued):
Sharing a sentence is not in itself a finding about the gene and the disease.
infection (continued). "Moreover, the absence of signals mediated by MyD88, TLR2, or TLR4 reduced nitric oxide synthase 2 (Nos2) mRNA expression during infection." (PMID 30555476, 2018). "Blocking TLR2, but not TLR4, and inhibition of PI3K, reduced cytokine production to near background levels in primary BMM and the murine RAW264.7 macrophage cell line responding to infection with P. gingivalis." (PMID 28848717, 2017). "A comparison of the infected and mock-infected WT and TLR2/9−/− groups showed that the overall production of perforin in the TG by several cell types (such as CD4+, CD8+, NK T and NK cells) was not statistically significant during infection." (PMID 28222752, 2017). "Interestingly, TLR2 expression in uninfected cells from BALB/c mice wassignificantly higher (>80%), and infection with L. major did not significantly increase the receptorexpression." (PMID 25738770, 2015). "Although it is well-known that LTA specifically targets TLR2, it is not certain whether during an S. aureus haemolytic infection, the extracellular metHb (with/without LTA) specifically signals via TLR2." (PMID 26137562, 2015). "For example, when TLR2 KO T-cells are adoptively transferred into wild-type recipients, CD8+ T-cells undergo decreased clonal expansion and failed to develop into long-lived memory cells upon vaccina infection." (PMID 25250027, 2014). "In the case of HSV infections, present results indicate a nonessential role for TLR9 during most infections, albeit TLR9 may together with TLR2 play a role for control of HSV brain infection in mice." (PMID 23435233, 2013). "Together uncontrolled infection and enhanced but ineffective inflammation induces increased severity and persistence of infection and disease that is most prominent in the absence of TLR2 combined with the presence of TLR4 i.e. in TLR2−/− compared to Wt and TLR4−/− or 2/4−/− mice." (PMID 22724018, 2012). "Mice lacking TLR2 exhibit an intrinsic defect in the number of CD4+CD25+Treg subset that maintains peripheral tolerance, but may also dampen the immune response to infection." (PMID 23189270, 2012). "However, TLR4−/− and MyD88−/− mice, and also wild-type, TLR2−/− and TRIF−/− mice, were refractory to infection when exposed to C. difficile without any prior antibiotic treatment (data not shown)." (PMID 21738466, 2011). "Interestingly, although mice simultaneously lacking TLR2 and TLR9 are highly vulnerable to infection, their mortality rate is still less than that of Myd88−/− mice, pointing to the involvement of other TLRs and/or IL-1/IL-18 in the control of mortality." (PMID 20442858, 2010). "However, the absence of increase in viral burden observed at day 3 in mice lacking TLR2 indicates that other mechanisms dependent on MyD88 signaling may be involved in viral clearance since an increase in viral titers was observed in MyD88−/− mice at both 3 and 5 days post-infection." (PMID 21060793, 2010). "However, intracellular replication in TLR4, TLR2 and TLR4/2 knockout cells was not altered and the infection course and anti-Brucella immunity development upon BrLPS injection was unaffected in TLR4 mutant mice." (PMID 17637846, 2007). "However it was infection of TLR2−/− mice with the non-lethal P. chabaudi AS line or the non-lethal P. yoelii XNL line that indicated there was very little impact on control of circulating iRBCs and the pathogenesis of infection." (PMID 36146602, 2022). "However, expression of TLRs at the apical surface of MECs seems to be rather low in healthy glands, as immunohistochemistry analysis of mammary tissue did not reveal expression of TLR2 or TLR4, contrary to strong expression early after infection or LPS challenge." (PMID 36341445, 2022). "TIGF infection with F. nucleatum induced IL-6 and IL-8 secretion in TIGFs, albeit to a lesser extent than in primary cells, indicating that TIGFs are capable of responding to infection through TLR4, but this response is diminished compared to primary cells in the absence of TLR2." (PMID 34031466, 2021).
infection (continued). "To that end, we stimulated different TLRs with their known ligands (e.g. TLR2 was stimulated with Pam3Csk4; TLR4 was stimulated with LPS, TLR7 was stimulated with imiquimod and TLR9 was stimulated with CpG-DNA) in the presence or absence of stimulation with Rv2463 or infection with M. tb H37Rv." (PMID 25915405, 2015). "Interestingly, TLR2−/− macrophages did undergo inflammasome-dependent cell death after F. novicida infection, in contrast to ASC−/−, caspase-1−/−and AIM2−/− macrophages, which do not die up to 14 h post-infection (and data not shown)." (PMID 21698237, 2011). "Similarly, the non-encapsulated strain activated both TLR2 and TLR6 within 10 h of infection." (PMID 21635729, 2011). "Moreover, TLR2−/− mice consistently appeared sicker (hunched back, ruffled fur and slow in movement) than control mice, and two out of 20 infected TLR2−/− mice (10%) succumbed between day 4 and 6 after infection, while none of control mice died." (PMID 21935459, 2011). "We observed that TLR2 was induced in alveolar macrophages from nonsmokers in response to PA infection but remained unchanged in smokers as well as in COPD and COPD + ICS patients, which might indicate a common situation in these individuals in which the TLR2 response to infection is compromised." (PMID 35897707, 2022). "Moreover, infection of human moDCs with H. pylori rapidly induces SOCS3 expression, which requires the type IV secretion system (T4SS), release of TNFα, and signaling via the MAP kinase p38, but appears to be independent of TLR2, TLR4, MEK1/2 and STAT proteins." (PMID 33023610, 2020).
tumor (549 papers, 2008 to 2026). "Galactan from Cantharellus cibarius drives M1-like polarization in tumor-associated macrophages, inhibiting cancer cell proliferation via TLR2 activation." (PMID 41235105, 2025). "Since aspirin is an HMGB1 inhibitor, and we have shown that TLR3 activation induces TLR2 expression, it is possible that the observed effect of the HMGB1 inhibitor on tumor sphere survival is linked to TLR2 and its inability to be activated with its ligand." (PMID 40647457, 2025). "Metastasis of the LLC also involves the powerful stimulation of tumor-associated macrophages, which produce IL-6 and TNFα by activating TLR-2 and TLR-6." (PMID 38891915, 2024). "TLR2/4 pathway has been reported to influence chronic inflammation in tumors, activates dendritic cell traffic and its associated tumor-specific, cytotoxic T-cell responses in the TIME21, and reduces tumor progression through multiple mechanisms." (PMID 38424363, 2024). "Positive intratumoral CD3T and CD8T levels, and a high CD3–CD8 tumor–stroma index associated and correlated with a high TLR2 and a high TLR4 immunoexpression." (PMID 36649244, 2023). "Previous studies have indicated that TLR2 deficiency or the presence of TLR2 antagonists can effectively inhibit tumor growth." (PMID 37925462, 2023). "CCL5, VCAM1, and TLR2 have been demonstrated to be associated with the tumor immune microenvironment and promote PCa cell metastasis." (PMID 37494663, 2023). "A high tissue TLR2 immunoexpression associated with a higher CD3–CD8 tumor–stroma index (p < 0.001; chi-square test), with a weak positive correlation (rs = 0.157; p < 0.001)." (PMID 36649244, 2023). "TLR2 is expressed in tumor-associated macrophages (TAM) of HCC and contributes to autophagy in the regulation of M2 macrophage polarization by high-mobility group box 1 (HMGB1)/NADPH oxidase 2 (NOX2) axis." (PMID 37020586, 2023). "Toll-like receptor-2 (TLR2) deficiency is associated with autophagy inhibition and subsequently results in the biosynthesis of M2-type macrophages, which in turn supports tumor progression." (PMID 36160153, 2022). "Our results corroborate other studies of tumor growth in Tlr2- and Tlr4-deficient mice, suggesting that Tlr deficiency mitigates tumor progression." (PMID 34032639, 2021). "Versikine can engage G1 cell-surface targets such as TLR2 on macrophages stimulating anti-tumour immunity, emphasising its role as a damage-associated molecular pattern (DAMP)." (PMID 34527586, 2021). "It is proposed that a decrease in cardiomyocyte defense mechanisms against ER stress contributes to Dox susceptibility in hearts from tumor-bearing animals and is suggested to be controlled by iNOS-regulated TLR2 activity." (PMID 34943000, 2021). "A recent study also showed that the tumor expressing high level of TLR2 and TLR4 in colorectal cancer patients was associated with a worse disease." (PMID 33898309, 2021). "Helicobacter pylori is the most extensively studied bacterial etiological factor in gastric adenocarcinoma and colon cancer, causing tumor onset and progression by upmodulating TLR2 on intestinal epithelial cells, which accelerates their proliferation." (PMID 34604233, 2021). "The mRNA expression levels of TLR2 were associated with tumor size, subtypes, and TNM stage (all P < 0.05)." (PMID 32426275, 2020). "TLR2 is upregulated in most tumors and closely associated with tumor metastasis, playing an important role as a proto-oncogene." (PMID 32426275, 2020). "The activation of NF-κB, which is commonly induced by TLR2/MyD88, has been linked to the progression of tumours." (PMID 32760436, 2020). "It has been reported that the TLR2-regulated gene signature is associated with tumour growth and that TLR2-dependent inflammation mediates tumour metastasis." (PMID 32760436, 2020). "TLR2 associated with the tumor location (p = 0.042) and the tumor grade (p = 0.004, chi-square test)." (PMID 32424768, 2020).
tumor (continued). "Our in vitro data (waiting to be published) together with the in vivo data from the current study showed that Arr2 was associated with the increase of TLR2, explaining the possible mechanism of its positive regulation on tumor pathogenesis." (PMID 31675995, 2019). "Arr2 overexpression was associated with the increase of TLR2 and several inflammatory factors, meanwhile inhibited paclitaxel-induced anti-tumor effect on human EC heterotransplants." (PMID 31675995, 2019). "In the current study, we used paclitaxel to induce apoptosis of cancer heterotransplants in vivo, so as to reveal the function of Arr2 on tumor growth and associated molecular changes including the conflicting TLR2." (PMID 31675995, 2019). "tumor-derived microvesicles from several tumor cell lines modulate synthesis of interleukin-6 (IL-6) in MDSCs via the activation of Toll-like receptor 2 through the membrane-associated heat shock protein 72 (HSP 72)." (PMID 29868251, 2018). "HMGB1 and HSP70, the representatives of TLR2/4 ligands released from tumor cells, have been implicated in promoting the production of proinflammatory cytokines." (PMID 28415700, 2017). "Myeloid-derived suppressor cells and tumor-associated macrophages express TLR2 that activates MyD88 signaling to promote invasion and metastasis." (PMID 29041928, 2017). "While there is data that TLR2 has a pro-tumorigenic role in a model of HCC, there is also data pointing to an increased aggressive tumor behavior in HCC in TLR2 deficient mice." (PMID 25846753, 2015). "TLR2 expression has also been detected in human glioblastoma U87 cells with touchdown PCR and subsequently linked to tumor promotion." (PMID 25411122, 2014). "TLR2 has been implicated in the activation of pro-inflammatory cytokines that enhance tumour invasion and migration." (PMID 23866094, 2013). "In conclusion, a molecular mechanism underlying the TLR2-mediated anti-tumor effects involves, at least partially, the prevention of ROS accumulation and ER stress onset." (PMID 24098333, 2013). "The average tumor number per mouse was almost doubled in TLR2-deficient mice compared to WT mice (6.1 vs. 3.5, p<0.05)." (PMID 20885960, 2010). "Notably, TLR2 activation has been associated with tumor cell proliferation and inhibition of apoptosis." (PMID 40061903, 2025). "Autophagy is involved in the production and polarization of macrophages, and the deficiency of Toll-like receptor 2 (TLR2) is associated with the inhibition of autophagy, which subsequently leads to the biosynthesis of M2-type macrophages, thereby supporting tumor progression." (PMID 38918278, 2024). "Similarly, in a fibrosarcoma study, combining vaccination against tumor-associated antigens with TLR2 agonists resulted in an increase in CD8+ T cells and antibody production, with a concomitant reduction in Treg frequency." (PMID 38203626, 2023). "However, we have not shown direct evidence that impaired recruitment of myeloid cells to lung tumors underlies the tumor-promoting effects of Tlr2 loss in this context." (PMID 36351380, 2022). "Additionally, glioma-derived versican has been suggested to promote tumor expansion by stimulating Toll-like receptor 2 signaling in tumor-associated macrophages." (PMID 34944101, 2021). "Indeed, high TLR2 expression is significantly associated with advanced disease stage, the presence of distant metastasis and microvascular invasion, and large tumor size." (PMID 33321934, 2020). "In addition, tumor-derived exosome-containing heat-shock protein 72 is able to trigger the immunosuppressive function of tumor-associated myeloid cells via the TLR2/MyD88 pathway." (PMID 32788720, 2020). "TLR2 along with TLR1 or TLR6 on tumor-associated microglia mediates an immunosuppressive role by enhancing production of matrix metalloprotease (MMP) to facilitate tumor invasion." (PMID 33520994, 2020).
tumor (continued). "Furthermore, interesting findings have indicated a possible association between TLR2 and the release of inflammatory cytokines, which contribute to a permissive microenvironment for tumor progression." (PMID 31675995, 2019). "Because we observed significant inhibition of zymosan-induced tumor growth with an α-TLR2 mAb, we assessed if zymosan could induce the activation of signaling pathways downstream of TLR2." (PMID 25846753, 2015). "In addition, also, the TLR-2 (Toll-like receptor-2) has been associated with increased tumor progression and metastasis, as well as tumor angiogenesis." (PMID 24887580, 2014). "To test whether the increased tumor number in TLR2−/− mice was associated with the oxidative stress and/or ER stress, we measured the expression and distribution profiles of oxidative stress and ER stress markers." (PMID 24098333, 2013). "Therefore, in our model, although PepO could induce TLR2−/− BMDM to express iNOS, TLR2 deficiency could also inhibit tumor growth and partially concealed the tumor-killing effect of PepO-primed M2 macrophages." (PMID 37925462, 2023). "However, TLR2 activity causes an immunosuppressive effect, which promotes tumor progression." (PMID 34439871, 2021). "Thus, in TLR2-deficient mice, tumor inducing circumstances, such as AOM/DSS, may suppress crypt damage and promote proliferation by cytokines such as TGF-ß." (PMID 20885960, 2010). "Studies have shown that tumor-secreted proteoglycans activate the TLR2/TLR6 complex on macrophages, utilizing the body's innate immune system for immune evasion." (PMID 41328346, 2026). "In CRC, A. muciniphila suppresses tumor growth by inducing the activation of the TLR2/NF-κB/NLRP3 pathway and promoting the accumulation of M1 macrophages." (PMID 39966840, 2025). "First, its outer membrane protein‐derived Amuc activates the Toll‐like receptor 2 (TLR2) signaling pathway, thereby mediating anti‐tumor immune responses." (PMID 40119640, 2025). "Oral administration of Dendrobium officinale polysaccharide (DOP) promotes M1 polarization via TLR2 on TAMs, inhibiting tumor growth." (PMID 40948759, 2025). "Among these, the cystine/glutamate antiporter xCT and Toll-like Receptor 2 (TLR2) emerge as particularly promising due to their established role in tumor progression, therapy resistance, and immune modulation." (PMID 41375047, 2025). "Macrophages possess the capability to engulf ferroptotic tumor cells in a TLR2-dependent manner, a process that significantly aids in the therapeutic approach of tumor ferroptosis." (PMID 40285867, 2025). "In contrast, our findings indicate that SUP3-induced TLR2 activation in dendritic cells inhibits tumor growth by driving DC maturation and cross-presentation." (PMID 41291775, 2025). "Polysaccharide-K (PSK), approved in 1977, acts as a novel TLR2 agonist that mediates tumor inhibition via stimulation of CD8+ T cells and NK cells." (PMID 40806379, 2025). "Our previous study demonstrated that Hsp70, secreted by cancer cells, interacts with toll-like receptor 2 (TLR2) and triggers the upregulation of MerTK, thereby stimulating M2 MΦ polarization and contributing to tumor growth." (PMID 40227806, 2025). "In non-small cell lung cancer (NSCLC), tumour-derived ANXA2 activates Toll-like receptor 2 (TLR2) receptors and downstream signalling on tumour-associated neutrophils (TANs), subsequently promoting ARG1 expression." (PMID 40234383, 2025). "In breast cancer, HMGB1 enhances tumor stem cell self‐renewal capacity and promotes tumorigenesis and metastasis by activating TLR2, inducing IκBα phosphorylation, stimulating IL‐6 and TGF‐β secretion, and activating STAT3 and Smad3 signaling pathways." (PMID 41354099, 2025). "Inflammation, typically a host response to pathogens, can be triggered by endogenous mediators (cytokines/chemokines) through tall-like receptors like Tlr2 to promote tumor progression and metastasis." (PMID 40458726, 2025).